IL6 (interleukin 6)
Diseases named in the same sentence as IL6 in open-access papers (continued):
Sharing a sentence is not in itself a finding about the gene and the disease.
Cachexia (continued). "Although endotoxemia is observed during severe cachexia when IL-6 levels peak, endotoxin can independently induce hypogonadism." (PMID 24285707, 2013). "Work from our laboratory has shown the severity of cancer development and cachexia in the ApcMin/+ mouse is dependent on the cytokine IL-6, which is also thought to be a factor in the development of human cachexia." (PMID 24285707, 2013). "We have previously established the importance of circulating IL-6 for cachexia development in the ApcMin/+ mouse." (PMID 24285707, 2013). "In the ApcMin/+ mouse model of cachexia, the cytokine IL-6 is necessary for muscle wasting, and over-expression of circulating IL-6 in precachectic ApcMin/+ mice accelerates the development of cachexia." (PMID 22769563, 2012). "In experimental animal models, treatment with monoclonal antibody to IL-6 or IL-6 receptor significantly suppressed the development of cachexia in tumor-bearing mice." (PMID 23326296, 2012). "The reduction in muscle PGC-1α expression coincided with circulating IL-6 levels, being repressed by IL-6 over-expression before a reduction in oxidative capacity, and being further reduced with the progression of cachexia." (PMID 22769563, 2012). "In conclusion, our study revealed that the Kampo formula, hochuekkito, ameliorated experimental cancer cachexia in mice and inhibited the production of macrophage-derived cytokines, especially IL-6." (PMID 23326296, 2012). "We have shown IL-6 inhibition and exercise training can prevent the progression of cachexia in ApcMin/+ mice." (PMID 22769563, 2012). "In contrast, the serum IL-6 level was significantly upregulated in the cachexia murine model as compared to that in controls and was significantly decreased by the treatment with hochuekkito." (PMID 23326296, 2012). "Development of cachexia in pre-clinical mouse models and clinical data correlate with increased circulating IL-6." (PMID 22361433, 2012). "Raised levels of Interleukin (IL)-1β, IL-6, Tumor Necrosis Factor-alpha (TNF-α) are implicated as tumor-derived factors in cachexia." (PMID 22361433, 2012). "As well, IL-6 plays a substantial role in inducing cachexia in mice bearing the colon-26 cancer cell line and the uterine cancer line, Yomoto, as administration of IL-6 blocking agents reduce muscle wasting in those models." (PMID 21799891, 2011). "Of the top 20 Broad MSigDB canonical pathways up-regulated in both moderate and severe colon-26 cachexia, eight were related to inflammation, including the complement and coagulation pathways, IL-6, STAT3, JAK-STAT, cytokine and Toll-like receptor pathways." (PMID 21799891, 2011). "During the initiation of cachexia, circulating IL-6 (P = 0.02) and spleen weight (P<0.001) were increased slightly, compared to weight stable ApcMin/+ mice, and increased further with the progression to intermediate body weight loss (P<0.001)." (PMID 21949739, 2011). "The purpose of this study was to determine IL-6 regulation of muscle protein turnover during the initiation of and progression towards more severe cachexia in the ApcMin/+ mouse." (PMID 21949739, 2011). "This is the first report, to our knowledge, demonstrating that muscle autophagy-related degradation is related to the progression of cachexia and circulating IL-6 levels." (PMID 21949739, 2011). "Our current study provides further evidence that a surge in circulating IL-6 is critical for the progression of cachexia in the ApcMin/+ mouse." (PMID 21949739, 2011). "The patients had high CRP and IL-6 levels and low serum albumin levels, which are part of the suggested diagnostic criteria for cachexia, acknowledging that CRP and IL-6 mainly are markers of inflammation." (PMID 21483870, 2011).
Cachexia (continued). "Fiber supplementation obviously reinforces the colonic mucus layer and reduces circulating LPS-binding protein and IL-6 levels in cachexia model mice, suggesting that the modification of the colonic mucus barrier is a major contributor to the alleviation of systemic inflammation." (PMID 41526343, 2026). "Furthermore, TNF-α and IL-1 can enhance the activation of the IL-6 signaling pathway, further exacerbating the progression of cachexia." (PMID 41526343, 2026). "Indeed, for non-NHB patients, our findings suggest that GDF-15 is a marker for early cachexia and that IL-6 increases at a later stage in the cachectic continuum (i.e. when the patient has refractory disease)." (PMID 39989973, 2025). "Furthermore, administration of CJME in a CT26-induced cancer cachexia mouse model effectively normalized biochemical parameters related to cancer cachexia, suppressed IL-6 production, and improved the overall condition by inhibiting muscle and fat wasting." (PMID 40469669, 2025). "In mouse models, inflammatory cytokines such as IL-6 were elevated in mice with cachexia." (PMID 41009413, 2025). "On the one hand, cachexia (driven by the tumor and host immune response) clearly induces changes in the microbiome, e.g., IL-6 transgenic mice develop cachexia and concurrently exhibit altered gut microbiota, implying the host inflammatory environment shapes the microbiome." (PMID 40572244, 2025). "Fourth, young blood’s components may instead exacerbate the progression of the disease, such as high levels of GDF11 cause severe cachexia, death, cardiac and skeletal muscle wasting, TNF-α and IL-6 promote cardiac remodeling and inflammation generation." (PMID 40969375, 2025). "Furthermore, we have found that female mice have a differential response to IL‐6 and the development of cachexia involving intact ovary function." (PMID 40931444, 2025). "Similarly, in mouse cancer cachexia models, we observe IL-6–JAK–STAT-signalling-mediated induction of Pck1 and Pdk3 expression in the liver." (PMID 40275022, 2025). "Both BCAA and BCAA+Di‐Ala significantly reduced the elevation of plasma IL6 in moderate cachexia." (PMID 40448398, 2025). "However, most pre-clinical models of cachexia produce levels of circulating IL-6 that are significantly higher than what is commonly observed in patients with lung cancer." (PMID 41278737, 2025). "In a mouse model of cachexia, IL-6 was found to be necessary for barrier disruption." (PMID 40869331, 2025). "Similarly, strategies modulating IL-6 activity were suggested to be effective in reducing hepatic inflammation and the systemic effects of cachexia." (PMID 39596015, 2024). "IL-6 levels gradually increased with cachexia progression in the YES2 group." (PMID 39327432, 2024). "MPA was able to abolish cachexia and reduce systemic levels of IL-6." (PMID 39114348, 2024). "Additionally, it was noted that these infiltrating macrophages are associated with an increased production of pro-inflammatory cytokines such as TNF-α and IL-6, which can significantly alter liver function per se, aggravating cachexia." (PMID 39596015, 2024). "This may be due to the fact that in NSCLC patients with cachexia, IL-6, IL-1, and TNF-α reduce CD8+ tumor infiltrating lymphocytes and anti-tumor immunity." (PMID 38466657, 2024). "Therefore, decreases in IL-6 activity via suppression of NF-κB by curcumin have shown benefits in counteracting the effects of cachexia in mice." (PMID 38674936, 2024). "Thirteen days after inoculation with tumor cells, CHX207 mice exhibited key clinical features of cancer cachexia, including systemic inflammation, increased plasma IL-6 concentrations, increased energy expenditure, adipose tissue loss, skeletal muscle wasting, and weight loss." (PMID 39220755, 2024).
Cachexia (continued). "Interleukin (IL)-6 in LLC-exosomes induced the lipidolysis of 3T3-L1 adipocytes by activating the signal transducer and activator of transcription 3 (STAT3) and promoting the cachexia process and the neutralization of extracellular IL-6 prevented the lipolysis effects of LLC-exosomes." (PMID 38689293, 2024). "The authors found a significant increase in the number of CD-68-positive monocytes associated with increased IL-6 levels, when compared to liver samples from cancer patients without cachexia." (PMID 39596015, 2024). "In both the initial and later stages of cachexia, a previous study found a positive connection between serum IL-6 and FFA, indicating that in cachexia, weight loss might be induced by IL-6 by accelerating WAT lipolysis." (PMID 39000187, 2024). "However, CRS only requires a short-term duration of therapy, and further study is needed Into long-term durations of therapy in order to successfully treat IL6-mediated cachexia." (PMID 38254849, 2024). "Using this approach, we found that disrupted hepatic lipid metabolism is a key feature of early‐stage cachexia and that reversal of this deficit using two genetic models that block IL‐6 signalling, or a ketogenic diet (KD) intervention, was sufficient to prevent PDAC‐associated muscle loss." (PMID 38632714, 2024). "Elevated levels of cytokines, including TNFα, IL1, and IL6, can also play roles in cachexia." (PMID 38898221, 2024). "Thus, AP neurons represent a critical mediator of IL-6 function in the development of cancer cachexia." (PMID 38824130, 2024). "However, research using IL-6 transgenic mice has been equivocal, and IL-6-induced cachexia appears to require additional signals in what is presumed to be a highly complex process." (PMID 38689325, 2024). "Despite several roles of IL-6 in the context of cachexia, the exclusive targeting of IL-6 may encounter similar obstacles as anti-tumor necrosis factor (anti-TNF) therapy." (PMID 38334644, 2024). "Notably, miniCASCO-based cachexia severity and IL-6 levels were independent predictors of clinical response, PFS, and OS." (PMID 36831431, 2023). "Blocking JAK/STAT3 signaling inhibited skeletal muscle wasting in an IL-6-induced cachexia model." (PMID 37217930, 2023). "Notably, a number of cytokines such as Tumour necrosis factor (TNFα), Transforming growth factor β (TGFβ), and Interleukin 6 (IL-6) have been tied to the progressive wasting of muscle and adipose tissue through a process termed cachexia." (PMID 36899813, 2023). "Presently, the role of IL-6 in cachexia is discussed controversially." (PMID 36672405, 2023). "Additionally, pro-inflammatory cytokines (especially IL-1, IL-6, and TNF-α) were shown to be important factors in the development of cachexia, a hypercatabolic state associated with muscle and adipose tissue wasting." (PMID 37630845, 2023). "To investigate whether cancer cell‐derived IL‐6 is crucial for cachexia development, we deleted the Il‐6 gene from CHX207 cells (CHXIL6KO) using CRISPR‐Cas9 mediated gene editing." (PMID 36351437, 2023). "Indeed, cancer cachexia patients are exposed to elevated circulating IL-6 levels for weeks, while circulating IL-6 increases punctually after acute exercise." (PMID 35847939, 2022). "In fact, these failures may be explained in light of the fact that another cytokine, the leukemia inhibitory factor (LIF), has been shown to be involved in cancer cachexia at least in rodent models and to be dominant over IL-6." (PMID 36078078, 2022). "In APCmin/+ mice, it was shown that there is no development of cachexia when they lack IL-6, while overexpression of IL-6 promoted cancer cachexia, the latter being associated with increased levels of phosphorylated STAT3 in skeletal muscle tissue." (PMID 36499157, 2022). "In early and advanced cancer cachexia, serum IL6 and FFA were also significantly positively correlated, indicating that cachexia may be associated with lipid metabolism, but the specific mechanism is still unclear." (PMID 36081564, 2022).
Cachexia (continued). "Study has found that chronic inflammation mediated by TNF and IL-6 may promote the occurrence of cachexia in patients with GC." (PMID 36081564, 2022). "According to the data presented here, IL-6 could be here an important mediator between de-regulated metabolism in cachexia and inflammatory response in fibroblasts from the LV and SM regarding NLRP3 inflammasome activity." (PMID 35967380, 2022). "In conjunction with its role as a cachexia mediator, IL-1β impairs immune function in multiple ways including the stimulation of myeloid-derived suppressor cells (MDSCs) and the induction of IL-6 and IL-22 expression." (PMID 35743911, 2022). "Studies investigating pathways involved in the onset of cachexia found several cytokines, such as TNFα, IL-1, IL-6 and LIF, which might play an important role as biomarkers or targets for tailored treatment." (PMID 36078078, 2022). "Also, IL-6 impairs intestinal barrier function in mouse models of cachexia, leading to translocation of microbial compounds, which can promote systemic inflammation." (PMID 35205709, 2022). "These CCR1+ macrophages expressed cachexia mediators Tnf, Il1b, and Il6." (PMID 35031523, 2022). "Several studies examined the effect of IL‐6 inhibitors on cachexia." (PMID 35080147, 2022). "In many circumstances, locally produced IL-6 reached the peripheral circulation and elicited systemic effects such as cachexia and paraneoplastic syndrome (including fever, increased erythrocyte sedimentation rate, increased levels of C-reactive protein in serum, hypoalbuminemia)." (PMID 35406728, 2022). "In addition, IL-6 can also target adipose tissue, gut, and liver, evidencing its central role in cachexia (Narsale and Carson, 2014; Zimmers, Fishel and Bonetto, 2016)." (PMID 36158184, 2022). "Interestingly, these alterations are independent of anorexia in the C26 model, and the blocking of IL-6 not only counteracts cachexia progression but also restores microbiota dysfunction." (PMID 36158184, 2022). "Moreover, IL-6 is sufficient to induce cachexia in mice as well as lipolysis and atrophy in cultured adipocytes and myotubes, respectively." (PMID 33851955, 2021). "Interestingly, exercise can slow the progression of cachexia by inhibiting IL-6-induced AMPK activation." (PMID 33809200, 2021). "Several studies reported that IL-6 promoted skeletal muscle wasting in clinical and experimental cachexia, although it was also reported that low levels of IL-6 could promote activation of satellite cells and myotube regeneration." (PMID 34003837, 2021). "Indeed, a proteomic signature of IL-6 activity correlates to cachexia severity in patients with PDAC." (PMID 33851955, 2021). "Cytokines such as IL-6, TNF-α and IL-1β trigger inflammatory cascades which may play a role in the pathogenesis of chronic kidney disease (CKD)-associated cachexia." (PMID 34302016, 2021). "Interestingly, reduced expression and serum levels of interleukin (IL)-6 were also found, which is a proinflammatory cytokine involved in cachexia progression." (PMID 33805286, 2021). "For example, blocking IL-6 signaling in hepatocytes has been shown to prevent the formation of a pro-metastatic niche in the liver and to restore the ketogenic response that is impaired in the setting of cachexia." (PMID 34202272, 2021). "Further, to understand which miRNA could be crucial during the IL-6-induced atrophy, we performed a comparative analysis that identified miR-23a-5p and miR-497-5p also deregulated in skeletal muscle of cancer cachexia models." (PMID 34944037, 2021). "An increase in IL-6 is a well-established characteristic of the C26 model of cachexia." (PMID 34621740, 2021). "Indeed, we found that cachexia‐mediated induction of IL‐6 and TNF‐α, two key pro‐cachectic factors, was dampened by iNOS inhibition, despite not affecting alterations in macrophage levels, macrophage polarization, spleen swelling, and tumor size." (PMID 34096686, 2021).
Cachexia (continued). "Finally, we tested the combination of supra-physiological levels of IL-6 and palmitate (to model FA increases in cachexia) on C2C12 myotubes." (PMID 33851955, 2021). "The cachexia markers IL6 and GDF15 differ between ages in both mice and patients." (PMID 35008253, 2021). "Among cytokines, IL-6 exerts a prominent role as cachexia inductor." (PMID 34203023, 2021). "Furthermore, cohort studies mainly indicate TNF-α and IL-6 levels as cachexia markers (reviewed in:)." (PMID 33557173, 2021). "Nevertheless, its predictive value, in combination with other markers such as albumin, CRP, GDF‐15, or IL‐6, for instance, may represent an efficient signature for diagnosis of cachexia." (PMID 34427055, 2021). "Importantly, the cachexia phenotype was completely normalized in Il1β−/−/CKD mice relative to Il1β−/−/Sham mice whereas Il6−/−/CKD and Tnfα−/−/CKD mice still exhibited some degree of cachexia." (PMID 34302016, 2021). "The concept of a causal role of pro-inflammatory cytokines mediating cachexia in humans has only been addressed very limitedly and only in a few pathological conditions, using targeted therapeutics that deplete specific cytokines such as TNF-α and IL-6." (PMID 33329046, 2020). "Sipjeondaebo-tang can inhibit the production of IL-6 in a CT-26 cancer cachexia model." (PMID 32020864, 2020). "For instance, significant concentrations of IL-6 were detected in the serum of cachectic mice transplanted with a cachexia-inducing colon-26 adenocarcinoma (C26) subtype, where serum level of IL-6—but not that of TNFα–correlated with severity of the pathological status." (PMID 32195193, 2020). "However, chronically elevated IL6 has been proposed to induce protein catabolism and muscle wasting during ageing and cachexia." (PMID 32340146, 2020). "cTNT release may be under the control of pro-inflammatory cytokines, such as IL-6 and TNFα (both involved in C26-related cachexia), as also suggested by studies on how pharmacological blockade of these cytokines affects cTNT levels." (PMID 32824440, 2020). "While IL-6, another often implicated biomarker in cachexia was not differentially present, upstream regulator prediction and protein co-expression network analysis both identified IL-6 with high significance." (PMID 33334063, 2020). "While this study implies a causal contribution of TNF-α in skeletal muscle atrophy, this may result from indirect effects of TNF-α by increasing other cytokines such as IL-6 that contribute to cachexia development by impacting on skeletal muscle." (PMID 33329046, 2020). "Interestingly, this reliance upon IL‐6 for development of cachexia in the ApcMin/+ model appears to be sex specific, where more recent works demonstrate a lack of IL‐6 dependence in the female mouse." (PMID 33063952, 2020). "Intraperitoneally injected matrine (50 mg/kg for 5 or 11 days from the onset of cachexia) in C26-bearing mice lowered serum levels of TNFα and IL-6 and preserved body and gastrocnemius muscle weights, downregulating the expression of atrogenes in skeletal muscle." (PMID 33255345, 2020). "These inferences suggest the diverse and critical role of IL-6 in cachexia." (PMID 33334063, 2020). "Moreover, it was demonstrated that female animals in the ApcMin/+ CRC model undergo cachexia, at least in part, independently of IL6." (PMID 31915140, 2020). "The investigation was focused on the changes in the levels of TNF-α and IL-6 in mouse serum and changes in the body weights and gastrocnemius muscle weights of cancer cachexia mice to investigate whether ginseng is helpful for treating cancer cachexia." (PMID 32020864, 2020). "In animal cachexia models, both plasma IL-6 and TNF-α were significantly increased." (PMID 31788012, 2019). "Similarly, when comparisons were made between female cancer cachexia and female non-cachexia patients, IL-6 and FFA were remarkably higher in the cachexia group, while BMI, total cholesterol, ApoE and prealbumin were apparently lower in the cachexia group." (PMID 31788012, 2019).